PON1 (paraoxonase 1)
Diseases named in the same sentence as PON1 in open-access papers (continued):
Sharing a sentence is not in itself a finding about the gene and the disease.
neurodegenerative disease (23 papers, 2017 to 2025). A disorder of the central nervous system characterized by gradual and progressive loss of neural tissue and neurologic function. "All but one patient (P1) showed the presence of variants already identified as risks factors for neurodegenerative diseases, rs662 (PON1) and rs5848 (GRN)." (PMID 34946792, 2021). "The low activity of PON1 has also been associated with several neurodegenerative diseases as well as lipid changes and demyelination process (in an animal model)." (PMID 33374313, 2020). "PON-1 and its ability to hydrolyze organophosphates were the first described associations between paraoxonase and the development of neurodegenerative diseases." (PMID 31052559, 2019). "The occurrence of PON1 in plasma and cerebrospinal fluid (CSF), as well as its antioxidant function, focused the interests of researchers on verifying a potential link between PON1 polymorphisms and the risk of developing neurodegenerative diseases." (PMID 39684839, 2024). "However, data on the association between single-nucleotide polymorphisms (SNPs) in the PON1 gene and cardiovascular or neurodegenerative diseases are insufficient." (PMID 39684839, 2024). "However, data on the association between SNPs in the PON1 gene and cardiovascular or neurodegenerative diseases are insufficient and contradictory." (PMID 39684839, 2024). "PON-1 possesses both anti-oxidant and anti-inflammatory properties, suggesting that a decrease in PON-1 activity might increase the risk for neurodegenerative diseases." (PMID 32963743, 2020). "PON1 activity and polymorphisms have been associated with neurodegenerative diseases." (PMID 33374313, 2020). "Furthermore, PON1 and its isoforms seem to play an important role in drug metabolism (including a number of important pharmaceutical agents such as statins or glucuronide drugs) and it has been associated with neurodegenerative diseases." (PMID 37958765, 2023). "PON1 exhibits a variety of physiological activities, making it an important role in the pathogenesis of neurodegenerative diseases." (PMID 33628379, 2021). "The antioxidant PON1 has an anti-inflammatory role and was documented in the serum, CSF, and brain, suggesting its activity in neurodegenerative disease." (PMID 34769107, 2021). "The involvement of PON1 in the pathogenesis of a variety of neurodegenerative diseases suggested that more research was needed to determine its exact pathogenic mechanism and its predictive value." (PMID 33628379, 2021). "PON1 isoforms play an important role in drug metabolism and the prevention of cardiovascular and neurodegenerative diseases." (PMID 33348669, 2020). "PON1 and its isoforms play an important role in drug metabolism as well as in the prevention of cardiovascular and neurodegenerative diseases." (PMID 33348669, 2020). "More research is needed to provide firm conclusions of the role of the PON1 as a biomarker in neurodegenerative diseases in DM." (PMID 32872672, 2020). "Therefore, future studies should investigate PON1 in the context of other neurodegenerative diseases." (PMID 36829958, 2023). "The PON1 lowering effects of smoking may contribute to inflammatory and oxidative burden, and thus, to the increased incidence of degenerative diseases." (PMID 35893041, 2022). "In addition to neurodegenerative diseases, the role of PON1 in AIS has attracted more and more attention." (PMID 33628379, 2021). "PON1’s antioxidant activity, its presence in both plasma and CSF, and the documented protein localization in certain regions of the brain suggest that PON1 could play a role in the pathogenesis of AD and other neurodegenerative diseases." (PMID 33287338, 2020). "Several studies have shown that PON1 status and oxidative stress could play important roles in many neurodegenerative diseases." (PMID 28694880, 2017).
neurodegenerative disease (continued). "However, we accounted for several potential confounding factors (e.g., age, gender, etc.)known to be associated with PON1, PON3, and neurodegenerative diseases, and the significant results observed were independent of these factors." (PMID 39456469, 2024).
neurological diseases (23 papers, 2016 to 2025). "Pon1 is an antioxidant gene involved in the reduction of lipid oxidation that is lower in AD patients but its polymorphism is a risk factor for neurological diseases." (PMID 41216177, 2025). "Dysregulation of these interactions by low PON1 activity can account for its association with cardiovascular and neurological diseases." (PMID 37175471, 2023). "Modulation of those interactions by the PON1 genotype can account for its association with cardiovascular and neurological diseases." (PMID 33260536, 2020). "The molecular basis of PON1 association with cardiovascular and neurological diseases is not fully understood." (PMID 33260536, 2020). "In a recent study dealing with a potential role of paraoxonase 1 (PON1), a high-density lipoprotein-associated enzyme, in the development of neurological diseases, the authors could show that B vitamins abrogated associations of PON1 with cognition." (PMID 35053277, 2022). "The PON1 polymorphism is associated as risk factor for neurological diseases." (PMID 28694880, 2017). "Thus, changes in APOD and APOM levels could contribute to the association of the PON1 genotype with cardiovascular and neurological diseases." (PMID 33260536, 2020). "Paraoxonase 1 (PON1) is an antioxidant enzyme, which has been proved to be involved in the pathophysiological process of oxidative stress and various neurological diseases in recent years." (PMID 33628379, 2021). "Recent studies have shown that PON-1 activity declines in several neurodegenerative and neurological disorders." (PMID 35096303, 2021). "Aside from the unknown mechanism of PON1 transfer to the CSF, there have been very few studies measuring PON1 activity in the CSF in relation to AD, as well as to other neurological diseases." (PMID 33287338, 2020). "Findings of some studies have indicated that PON1 may play an important role in the pathogenesis of neurological disorders." (PMID 28694880, 2017). "Three main biomarkers, Paraoxonase-1 (PON-1) in CVD, Matrix Metalloproteases (MMPs) in both CVD and neurological diseases, and Beta-Secretase-1 (BACE-1) in AD have been proposed as indicator of sex-specific disease phenotypes." (PMID 38560614, 2024).
renal disease (22 papers, 2012 to 2025). "Oxidative stress and inflammation play an interactive role in renal disease and are mutually associated with altered PON-1 activity in plasma of patients with renal disease." (PMID 35624764, 2022). "Uremic components can interfere with HDL structure, and since in renal disease their elimination is reduced, it will lead to lower PON1 activity." (PMID 38474211, 2024). "There are multiple lines of evidence in the literature emphasizing or suggesting the importance of PON1 activity in kidney diseases." (PMID 38982880, 2024). "The native activity of PON1 is attributed to homocysteine-thiolactonase (lactonase), while the activities mostly measured in the laboratory for kidney diseases are those of paraoxonase and arylesterase." (PMID 38982880, 2024). "In this context, we sought to determine the role of diminished PON-1 as a potential factor in the development and progression of renal diseases in a well characterized model of high-salt induced renal disease." (PMID 35624764, 2022). "In the current study, we used a novel SS-PON-1 KO rat model to examine the role of PON-1 in a well-characterized model of high-salt induced renal disease." (PMID 35624764, 2022). "Modulation of PON-1 levels and activity may present a novel therapeutic break to modulate the inflammatory events which contribute to the initiation and progression of renal disease." (PMID 35624764, 2022). "Augmenting endogenous counter-regulatory mechanisms such as PON-1 may provide a unique therapeutic opportunity to attenuate renal disease progression." (PMID 35624764, 2022). "This phenomenon may be explained by potentially lower PON1 activity in kidney disease." (PMID 25155309, 2016). "Renal disease patients show significantly reduced plasma HDL-C, APOA-I, serum PON1 protein concentration, PON1 arylesterase/ paraoxonase activity, and LCAT activity, indicating the impaired interactions of PON1 with APOAI and LCAT in dysfunctional HDL in these patients." (PMID 39594433, 2024). "In our study, we observed no significant change in the PON-1 and MPO activity along the progress of kidney disorders." (PMID 30857306, 2019).
metabolic disease (19 papers, 2017 to 2025). A congenital disorder (due to inherited enzyme abnormality) or acquired (due to failure of a metabolically important organ) disorder resulting from an abnormal metabolic process. "The bonding between HDL and PON1 is influenced by some apolipoproteins such as apoA-1 and ApoJ, which are implicated in metabolic diseases, and the bonding is promoted by scavenger receptor class B type I (SR-BI)." (PMID 38474211, 2024). "Among the PON family, PON1 shows the strongest association with metabolic disorders, functioning as a key regulator of glucose and lipid homeostasis." (PMID 39334710, 2024). "Furthermore, PON1 harbors anti-inflammatory and antioxidant capacities and has been implicated as a potential therapeutic target for treating various metabolic diseases." (PMID 37189434, 2023). "The protective effect of vutiglabridin on PON1 appears to have been amplified in the obese and hyperlipidemic mice, suggesting the strong therapeutic potential of vutiglabridin against metabolic diseases." (PMID 37189434, 2023). "Presenilin 1 (PSEN1), catalase (CAT), glutathione-S-transferase (GST) andparaoxonase 1 (PON1) play a vital role in prediction, diagnosis and therapyof metabolic disorders." (PMID 35976206, 2022). "Its role is to degrade toxic organophosphates and metabolize oxidized lipids, and lower levels of PON1 have been correlated with the metabolic disease." (PMID 32708089, 2020). "These will also help in discovering new regulators of PON1 levels and activity, in order to avoid metabolic disorders progression into more serious pathophysiological states." (PMID 31430977, 2019). "The aim of this review is to elucidate the physiological role of PON1, as well as the impact of altered PON1 levels in metabolic disorders." (PMID 31430977, 2019). "Apart from its antioxidant effects, PON1 has multiple implications in metabolic disorders due to the fact of its promiscuous multiple activities." (PMID 31847187, 2019). "Oxidative stress and inflammation, which are hallmarks of metabolic disorders, have a profound impact on PON1 levels and activity." (PMID 31430977, 2019). "Undeniably, metabolic disorders with a prooxidant component lead to the increase of ROS and, hence, result in increased oxidative stress and decreased PON1 antioxidant activity and bioavailability." (PMID 31430977, 2019). "Therefore, metabolic diseases that lead to high ROS levels decrease PON1 levels and its ability to stop LDL oxidation and the activation of pro-inflammatory cells." (PMID 38474211, 2024). "Metabolic disorders are characterized by an overall state of inflammation and oxidative stress, which highlight the importance of a functional antioxidant system and normal activity of some endogenous enzymes, namely paraoxonase-1 (PON1)." (PMID 31430977, 2019). "Therefore, in metabolic disorders, the activity of PON1 and anti-inflammatory and anti-atherosclerotic properties of serum HDL-PON1 complex are significantly decreased due to inactive oxidation and glycation of both free PON1 and HDL-PON1." (PMID 31430977, 2019). "SR-BI deficiency leading to dysfunctional HDL is closely related to alteration of HDL protein, suggesting that identification of apoAI, PON1, SAA, apoAIV, and A1AT may serve as the valuable protein markers for diagnosis and therapeutics of dysfunctional HDL-related metabolic diseases." (PMID 29879989, 2018). "Thus, the decrease in PON-1 observed in diabetic CAD patients compared to nondiabetic could be both a downstream and upstream event linked to either glycation or oxidative stresses that characterize the metabolic disease." (PMID 35308142, 2022).
heart disease (12 papers, 2014 to 2024). "PON1 is an enzyme with antioxidant and anti-atherogenic properties, whose reduced activity has been linked to heart disease in humans." (PMID 30487467, 2018). "It has been reported that paraoxonase 1 activity was decreased in heart disease, and a large number of studies have been conducted over the last two decades to demonstrate the relationship of paraoxonase 1 activity and the susceptibility to DM and DM complications." (PMID 29981194, 2018). "The current study highlights the roll of endogenous PON-1 in preventing cardiac disease in a well-established model of CKD." (PMID 36140402, 2022). "Based on this background, we aimed to examine the role of PON-1 as a possible factor in mediating cardiac disease in a well-established model of high-salt-mediated CKD." (PMID 36140402, 2022). "On the other hand, lowering of PON-1 activity was associated with an increase in LVIDdn and LVIDsn measurements, as well as MV E/A ratio, which are markers of advanced cardiac disease and decompensated heart failure, regardless of group." (PMID 36669034, 2023). "Hence, it provided conclusive evidence on the effects of propofol on heart disease by altering the activity of PON1." (PMID 27437027, 2016).
bacterial infection (6 papers, 2009 to 2022). "Both PON1 and natural IgM are first line innate immune defenses against bacterial infections and display strong anti-inflammatory and antioxidant properties, explaining that impairments in both systems contribute to FEP/FES." (PMID 34831151, 2021). "For example, three lactonases are present in humans: PON1, PON2 and PON3; of these, only PON2 is expressed in all tissues, and it appears to be involved in the first step of defense against bacterial infection." (PMID 32993120, 2020).
infectious disease (6 papers, 2012 to 2025). A disorder directly resulting from the presence and activity of a microbial, viral, or parasitic agent in humans. "In veterinary medicine, PON-1 has been used for monitoring infectious diseases, for prognostic purposes, and, more recently, in non-infectious diseases." (PMID 39409835, 2024). "In several non-communicable and infectious diseases, changes in PON1 activity are the cause or consequence of alterations in the inflammatory state of the organism." (PMID 35740079, 2022). "We have already observed changes in the opposite direction of the activity and concentration of PON1 in other infectious and non-infectious diseases that involve oxidative stress, and we interpret them as an attempt by the organism to counteract the decrease in enzyme activity." (PMID 34205807, 2021). "Similar findings were described in other infectious diseases when compared to the healthy controls after 4 months of follow-up, mostly characterized by low HDL-c levels and low paraoxonase-1 activity." (PMID 36499671, 2022).
inflammation (6 papers, 2013 to 2025). Aberrant reaction of the microcirculation characterized by movement of fluid and leukocytes from the blood into extravascular tissues. "Reduced expression and activity of PON1 were linked to oxidative stress, lipid dysregulation, and liver inflammation." (PMID 41374408, 2025). "Changes in plasma PON1 levels are also associated with liver cell destruction and chronic inflammation." (PMID 33046970, 2020). "Consistent with our results regarding low PON1 activity in the high HDL-C/high CRP subgroup many other disease states associated with low-grade chronic inflammation also manifest low PON1 activity." (PMID 31480611, 2019). "We have showed, previously, that PON1 inhibits MCP-1 induction in endothelial cells, which suggested a protective role against liver inflammation mediated by MCP-1." (PMID 23766557, 2013).
adenocarcinoma (2 papers, 2015 to 2017). A common cancer characterized by the presence of malignant glandular cells. "In 8 matched cases, SCC tissues revealed a shallow overexpression (in densitometry) than adjacent normal tissues, while in 16 matched cases of adenocarcinoma, PON1 is minimally decreased." (PMID 28467805, 2017). "Supporting this, we were able to observe higher focal, specific amplification at the PON1 locus in SCC than in adenocarcinoma." (PMID 28467805, 2017). "In the lung SCC cohort, PON1 has relatively high amplification of DNA copy numbers in all SCC variants (348 general SCC samples; 8 SCC, basaloid variant samples; 2 SCC, papillary variant samples; 1 SCC small cell variant sample) compared to both lung normal (no value) and the adenocarcinoma cohort." (PMID 28467805, 2017).
mental illness (2 papers, 2020 to 2022). "Inadequate levels of 5-methyltetrahydrofolate (5-MTHF) and the T variant of MTHFR C677T have been suggested to be associated with an increased risk of developing mental illness, whereas the PON1 SNP variant provides a protective role." (PMID 36014826, 2022). "This may be linked to existing evidence of the involvement of specific polymorphisms of genes, such as CYP2D6, NAT2, and PON1, both in cellular detoxification and pathophysiology of psychiatric disorders and MCS, although further studies on these aspects are needed." (PMID 32916833, 2020).
neurodevelopmental disorder (2 papers, 2020 to 2021). A behavioral and cognitive disorder with onset during the developmental period that involves impaired or aberrant development of intellectual, motor, or social functions. "Several studies have investigated the association between neurodevelopmental disorders and PON1 enzyme activity and/or gene polymorphisms." (PMID 33499329, 2021). "In this work, we measured the PON1 arylesterase activity in newly-recruited samples of patients diagnosed with different neurodevelopmental disorders, namely ASD, ADHD, and SLI, as well as healthy controls." (PMID 33499329, 2021). "Our study was designed with two main purposes, namely: (A) to replicate in an independent sample the strong association observed in our previous work between reduced serum arylesterase activity and ASD, and (B) to extend our investigation of PON1 roles to other neurodevelopmental disorders." (PMID 33499329, 2021).
liver (1 paper, 2013). "As the liver plays a key role in the synthesis of serum PON1, it is plausible that there is an association between serum PON1 activity and liver impairment during fatty liver development in dairy cows." (PMID 23578174, 2013).
PON1 also shares sentences with these, for which no sentence is quoted: acute myocardial infarction (6 papers); polycystic ovary syndrome (5); hypertriglyceridemia (3); infarction (3); joint disease (3); leptospirosis (3); non-Hodgkin lymphoma (3); retinopathy (3); allergic disease (2); ankylosing spondylitis (2); Behcet disease (2); beta thalassemia (2); Brain atrophy (2); brain diseases (2); cardiac hypertrophy (2); cardiomyopathy (2); Cerebral ischemia (2); cerebrovascular disease (2); chorioamnionitis (2); chronic hepatitis (2); chronic hepatitis B (2); Chronic Kidney Failure (2); head and neck cancer (2); hematologic cancer (2); hemorrhagic stroke (2); Hyperinsulinemia (2); iron overload (2); knee osteoarthritis (2); liver fibrosis (2); parasitemia (2).
A further 106 diseases each share a sentence with PON1 in 2 papers or fewer.